IQGAP3 (IQ motif containing GTPase activating protein 3)
Diseases named in the same sentence as IQGAP3 in open-access papers (continued):
Sharing a sentence is not in itself a finding about the gene and the disease.
glioma (3 papers, 2017 to 2024). A benign or malignant brain and spinal cord tumor that arises from glial cells (astrocytes, oligodendrocytes, ependymal cells). "Abnormal expression of IQGAP3 has been linked to various tumors, but its function in glioma is not well understood." (PMID 38560572, 2024). "Various genetic alterations of IQGAP3 have been identified in glioma, including missense mutations, copy number increases, and amplifications." (PMID 38560572, 2024). "In summary, IQGAP3 is highly expressed in glioma to varying degrees and is associated with poor prognosis and several clinical features." (PMID 38560572, 2024). "Subsequently, a comprehensive investigation was performed to elucidate the interplay between IQGAP3 expression and distinct genomic attributes, notably somatic mutations, within the TCGA glioma dataset." (PMID 38560572, 2024). "This suggests that IQGAP3 expression is associated with reduced immune and stromal cell infiltration in glioma, leading to higher tumor purity." (PMID 38560572, 2024). "Experimental validation was also performed to assess the effects of IQGAP3 on glioma cells and explore underlying mechanisms." (PMID 38560572, 2024). "In addition, IQGAP3 expression was associated with higher glioma purity, which is a key factor affecting the response to immunotherapy and prognosis of patients, and high tumor purity was associated with poor prognosis of patients." (PMID 38560572, 2024). "We leveraged bioinformatics methodologies in conjunction with numerous publicly available databases to unravel the potential oncogenic significance of IQGAP3 in gliomas, including its expression, diagnostic, prognostic, genetic alterations, immune cell infiltration, and targeted drugs." (PMID 38560572, 2024). "Furthermore, we observed that knocking down IQGAP3 leads to reduced expression of proteins associated with the PLK1/PI3K/AKT pathway in glioma cells." (PMID 38560572, 2024). "Therefore, overexpression of IQGAP3 in glioma is significantly associated with poor prognosis in patients and serves as an independent prognostic factor for glioma patients." (PMID 38560572, 2024). "Secondly, our research solely offers preliminary evidence regarding the association between IQGAP3 and glioma, necessitating further experimental validation to unravel the precise molecular functions and mechanisms through which IQGAP3 influences the occurrence and progression of glioma." (PMID 38560572, 2024). "Utilizing the IQGAP3 expression profiles in glioma specimens, patients were classified into cohorts denoting heightened and diminished expression levels." (PMID 38560572, 2024). "In conclusion, our findings suggest that IQGAP3 knockdown can suppress the progression of glioma cells in vitro." (PMID 38560572, 2024). "The results demonstrated that IQGAP3 is highly expressed in glioma cell lines and that knocking down IQGAP3 significantly inhibits the proliferation and migration of glioma cells." (PMID 38560572, 2024). "The multivariate Cox regression analysis revealed that IQGAP3 was an independent prognostic factor for glioma patients." (PMID 38560572, 2024). "The resultant findings consistently revealed a noteworthy trend: heightened IQGAP3 expression correlated with an unfavorable prognosis in the context of glioma patients, encompassing diverse dimensions of survival including OS, DSS, and PFI." (PMID 38560572, 2024). "The impact of IQGAP3 on immune infiltration and the immune microenvironment in gliomas was evaluated using immunofluorescence." (PMID 38560572, 2024). "The expression of IQGAP3 in human glioma cell lines, SHG-44, CRT, U251, and human brain microvascular endothelial cell line HBMEC, was analyzed through RT-qPCR." (PMID 38560572, 2024).
glioma (continued). "Based on the average expression of IQGAP3, we categorized all glioma samples into high-expression and low-expression groups." (PMID 38560572, 2024). "Scatter plots demonstrated the strongest correlation between IQGAP3 expression and Th2 cells in gliomas, including GBMLGG (r = 0.845, p < 0.001), GBM (r = 0.572, p < 0.001), and LGG (r = 0.793, p < 0.001)." (PMID 38560572, 2024). "To identify promising small-molecule drugs targeting IQGAP3 in glioma, we uploaded the top 10 overlapping genes from IQGAP3 differential expression and correlation analysis to the Cmap online tool." (PMID 38560572, 2024). "In order to assess the potential impact of IQGAP3 on the survival outcomes of individuals diagnosed with glioma, a comprehensive analysis was conducted utilizing the Kaplan-Meier survival curve methodology." (PMID 38560572, 2024). "The expression of IQGAP3 was stronger in high-grade gliomas, with expression levels exceeding 75%, whereas it exhibited moderate intensity in low-grade gliomas, with expression levels greater than 50%." (PMID 38560572, 2024). "Transwell experiments indicated that knocking down IQGAP3 reduced the number of glioma cells involved in migration and invasion." (PMID 38560572, 2024). "Through bioinformatics analysis, we explored the diagnostic, prognostic, genetic alterations, immune infiltration levels, and biological functions of IQGAP3 in glioma." (PMID 38560572, 2024). "The results displayed positive nuclear staining for IQGAP3 in both high-grade and low-grade gliomas (with some cytoplasmic and membranous expression)." (PMID 38560572, 2024). "In summary, IQGAP3 likely plays a crucial role in initiating and progressing glioma through multiple cancer-related pathways, including the PLK1/PI3K/AKT pathway." (PMID 38560572, 2024). "In an effort to delve deeper into the influence of IQGAP3 on glioma cell proliferation, invasion, and migration capabilities, U251 cells were transfected with shRNA targeting IQGAP3." (PMID 38560572, 2024). "Based on previous bioinformatics analysis, we identified that IQGAP3 regulates several crucial signaling pathways in glioma." (PMID 38560572, 2024). "To reveal the possible biological role of IQGAP3 in gliomas, we conducted enrichment analysis using 599 RDEGs." (PMID 38560572, 2024). "This study provides a comprehensive analysis of IQGAP3 in gliomas based on multi-omics data and in vitro experiments." (PMID 38560572, 2024). "Furthermore, we utilized the Cmap online tool to identify small-molecule drugs targeting IQGAP3 for combating glioma." (PMID 38560572, 2024). "BRD-K88742110 and LY-303511 are potential drugs for targeting IQGAP3 in anti-glioma therapy." (PMID 38560572, 2024). "In conclusion, the roles of IQGAP3 in immune therapy and targeted treatment may provide valuable insights for future glioma therapies." (PMID 38560572, 2024). "Therefore, this research delved into the potential mechanisms through which IQGAP3 exerts its influence on gliomas, with a specific focus on genetic and epigenetic alterations." (PMID 38560572, 2024). "In summary, BRD-K88742110 and LY-303511 may be potential IQGAP3-targeting drugs, offering new directions for small-molecule drug development in glioma." (PMID 38560572, 2024). "In vitro experiments have confirmed the oncogenic function of IQGAP3 in glioma." (PMID 38560572, 2024). "Our results indicate that compared to non-tumor tissue, IQGAP3 has higher diagnostic accuracy in glioma." (PMID 38560572, 2024). "Our findings revealed a significant upregulation of IQGAP3 in glioma specimens (p < 0.001)." (PMID 38560572, 2024). "Therefore, we assessed the correlation between immune, stromal, and ESTIMATE scores with IQGAP3 expression levels in glioma." (PMID 38560572, 2024). "Implying that genetic modifications instigated by IQGAP3 in gliomas may further hasten glioma progression." (PMID 38560572, 2024).
glioma (continued). "In addition, a series of experimental validations were performed to evaluate the influence of IQGAP3 on various aspects of glioma biology, including proliferation, migration, and key signaling pathways." (PMID 38560572, 2024). "Additionally, experimental results demonstrated that IQGAP3 influences glioma cell proliferation, invasion, and migration, and is involved in various pathways in glioma development." (PMID 38560572, 2024). "Targeting IQGAP3 may improve the prognosis of glioma patients and bring new hope for cancer immunotherapy." (PMID 38560572, 2024). "Consequently, an estimation was conducted to determine the relative proportions of 25 distinct immune cell types within glioma, followed by an analysis of the correlation between the expression of IQGAP3 and these immune cell populations." (PMID 38560572, 2024). "This study is the first to investigate IQGAP3 as a biomarker in glioma." (PMID 38560572, 2024). "Immunohistochemical images of IQGAP3 in glioma samples were retrieved from the HPA database." (PMID 38560572, 2024). "Additionally, IQGAP3 expression shows significant correlations with tumor immune microenvironment, multiple immune markers, and various cancer-related signaling pathways in glioma." (PMID 38560572, 2024). "Hence, these two small-molecule compounds may play significant roles in anti-glioma therapy targeting IQGAP3, supporting personalized treatment approaches and clinical decision-making." (PMID 38560572, 2024). "Nonetheless, the function of IQGAP3 in gliomas remains unclear." (PMID 38560572, 2024). "The research findings indicate that IQGAP3 is associated with various immune cell types, particularly with CD4 Th2 cells and MDSCs present in all subtypes of gliomas, and the results of mIHC further validate the hypotheses generated from the bioinformatics analysis." (PMID 38560572, 2024). "In vitro experiments showed that downregulation of IQGAP3 inhibits the proliferation and migration of glioma cells, with the PLK1/PI3K/AKT pathway potentially playing a crucial role in IQGAP3-mediated glioma progression." (PMID 38560572, 2024). "Our results showed that IQGAP3 expression was positively correlated with immune checkpoint genes (PD1, PD-L1, B7-H3, TIM3) and most of the immune checkpoint-associated genes in gliomas, suggesting that IQGAP3 may be promising as a new immune checkpoint for gliomas." (PMID 38560572, 2024). "We analyzed the mRNA expression of IQGAP3 in 689 glioma specimens from the TCGA database and 1152 normal specimens from the TCGA database." (PMID 38560572, 2024). "However, the molecular mechanisms of IQGAP3 in relation to the PLK1/PI3K/AKT pathway in glioma have not been explored." (PMID 38560572, 2024).
lung adenocarcinoma (3 papers, 2015 to 2025). A carcinoma that arises from the lung and is characterized by the presence of malignant glandular epithelial cells. "Furthermore, Multivariate Cox proportional hazard analysis showed that a higher level of IQGAP3 was an independent risk factor for poor prognosis of the lung adenocarcinoma patients (hazard ratio=2.28, 95% confidence interval=1.25–4.14, P=0.007)." (PMID 26647728, 2015).
lymphoma (3 papers, 2021 to 2023). A malignant (clonal) proliferation of B- lymphocytes or T- lymphocytes which involves the lymph nodes, bone marrow and/or extranodal sites. "Therefore, on top of PI3K inhibition, adding a BET inhibitor that further attenuates RAS activation and also upregulates IQGAP3 could result in the death of lymphoma cells that mainly thrive on the activation of these pathways." (PMID 34638508, 2021). "Only in lymphoma did DLBCL patients with a higher expression of IQGAP2 have a worse prognosis, and IQGAP3 overexpression was correlated with an excellent prognosis." (PMID 36831467, 2023). "In patients whose lymphoma cells lacked active PI3K signaling, the expression of IQGAP3 did not predict any survival outcome." (PMID 36831467, 2023). "In patients whose lymphoma cells lacked activated PI3K signaling (group A), the expression level of IQGAP3 did not harbinger any survival outcome implication." (PMID 34638508, 2021).
renal carcinoma (3 papers, 2014 to 2022). A carcinoma arising from the epithelium of the renal parenchyma or the renal pelvis. "Compared with the other two widely studied isoforms, only IQGAP3 showed increased expression in different subtypes of renal cancer than normal tissue, indicating its general function in renal cancer." (PMID 36275458, 2022).
clear cell renal cell carcinoma (2 papers, 2022 to 2024). "Extensive evidence substantiates the involvement of IQGAP3 in the inception and progression of diverse malignant neoplasms, with notable prominence in breast cancer, clear cell renal cell carcinoma, and lung cancer." (PMID 38560572, 2024).
colon cancer (2 papers, 2014 to 2024). "This study revealed that remimazolam promoted the cell-cycle progression and proliferation of HCT8 colon cancer cells by upregulating CDK1, PTTG1, CDC25C, CDK4, PLK1, PCNA, Ki67, RNASEH2B, FEN1, Cyclin D1,CD44 CDK2, CDKN3, CDC45, IQGAP3, and CDK6." (PMID 38725628, 2024).
glioblastoma (2 papers, 2017 to 2024). The most malignant astrocytic tumor (WHO grade IV). "For IQGAP3, higher expression levels were reported in glioblastoma subtype only." (PMID 29073199, 2017). "Furthermore, IQGAP3 expression may be closely related to the immunosuppressive microenvironment of glioblastoma." (PMID 38560572, 2024). "The results showed that compared with adjacent non-tumor tissues, IQGAP3 was more widely expressed in glioblastoma." (PMID 38560572, 2024). "Nonetheless, the TCGA database analysis showed higher expression of IQGAP3 in glioblastoma (fold change = 3.08) but not in other subtypes of brain cancer." (PMID 29073199, 2017).
kidney cancer (2 papers, 2017 to 2019). Primary or metastatic malignant neoplasm involving the kidney. "The threshold level of IQGAP3 expression was not reached by any of the datasets available in Oncomine, but the TCGA datasets (KIRP-TCGA and KIRC-TCGA) available with Xena browser, showed high expression of IQGAP3 in kidney cancer, compared to the normal tissues." (PMID 29073199, 2017). "The mRNA expression of IQGAP2 and IQGAP3 was analysed among different cancer stages (I to IV) in lung, breast, stomach, colorectal, prostate, liver and kidney cancer, whereas the expression in brain cancer was compared between the histologic grades (G2 and G3) because of the lack of stage wise data." (PMID 29073199, 2017).
prostate carcinoma (2 papers, 2017 to 2023). A carcinoma that arises from epithelial cells of the prostate gland. "The mRNA expression of IQGAP3 did not cross the set threshold level of inclusion criteria in Oncomine database, but analysis with PRAD-TCGA dataset showed increase in its expression (fold change = 1.93) in prostate cancer tissues, compared to the normal." (PMID 29073199, 2017).
adrenocortical carcinoma (1 paper, 2022). "High expression of IQGAP3 was associated with poor overall survival (OS) in adrenocortical carcinoma (ACC), KIRC, KIRP, acute myeloid leukemia (LAML), brain lower-grade glioma (LGG), liver hepatocellular carcinoma (LIHC), LUAD, mesothelioma (MESO), and uveal melanoma (UVM)." (PMID 35274003, 2022).
brain cancer (1 paper, 2017). A primary or metastatic malignant neoplasm affecting the brain. "As far as prognosis is concerned, increase in both IQGAP2 and IQGAP3 mRNA levels correlated with poor overall survival of brain cancer patients." (PMID 29073199, 2017).
brain tumor (1 paper, 2017). "Strong staining was present in 36.7% of brain tumor samples, whereas no uninvolved area showed strong staining for IQGAP3." (PMID 29073199, 2017).
cervical cancer (1 paper, 2021). A primary or metastatic malignant neoplasm involving the cervix. "Interestingly, transcriptome analysis showed that IQGAP3 is significantly upregulated during lesion progression in HPV-positive cervical cancer tissue, further suggesting that IQGAP3 could be important in HPV-associated carcinogenesis." (PMID 34068608, 2021).
Cirrhosis (1 paper, 2016). A chronic disorder of the liver in which liver tissue becomes scarred and is partially replaced by regenerative nodules and fibrotic tissue resulting in loss of liver function. "In this study, we investigated CCT3 and IQGAP3 at plasma levels in patients with HCC or cirrhosis and in healthy individuals, and evaluated their application in detecting small and AFP-negative tumors in patients with HCC." (PMID 27390551, 2016). "IQGAP3 had sensitivity of 74.5 % when distinguishing small HCC from cirrhosis at a cut-off value of 43.5 pg/mL." (PMID 27390551, 2016). "In the plasma of HCC patients, both CCT3 and IQGAP3 were significantly higher than in patients with cirrhosis and in healthy controls (P < 0.01)." (PMID 27390551, 2016). "AUC for IQGAP3 was 0.822 (95 % CI 0.700–0.943, P < 0.01); when differentiating from cirrhosis, its sensitivity and specificity were 85.2 and 71.6 %, respectively, when the cut-off value was selected at 43.5 pg/mL." (PMID 27390551, 2016). "Similarly, expression of serum IQGAP3 in patients with HCC (266.71 ± 178.47 pg/mL) was evidently higher (P < 0.001) than that in patients with cirrhosis (66.44 ± 63.97 pg/mL), or healthy controls (59.50 ± 51.08 pg/mL)." (PMID 27390551, 2016). "Blood samples were collected from 126 HCC patients with HCC, 88 patients with cirrhosis and 50 healthy volunteers to detect plasma α-fetoprotein (AFP), CCT3 and IQGAP3 levels." (PMID 27390551, 2016). "In addition, plasma CCT3 and IQGAP3 from 38 AFP-negative HCC and 88 cirrhosis patients were analyzed." (PMID 27390551, 2016).
diffuse gastric adenocarcinoma (1 paper, 2017). An adenocarcinoma arising from the stomach. "However, TCGA database showed increased IQGAP3 mRNA expression in gastric intestinal adenocarcinoma (fold change = 3.25), diffuse gastric adenocarcinoma (fold change = 2.51) and gastric mixed adenocarcinoma (fold change of 2.43)." (PMID 29073199, 2017).
gastrointestinal stromal tumor (1 paper, 2020). "None of the non-cancerous gastric tissues or gastrointestinal stromal tumors (GIST) expressed IQGAP3 protein." (PMID 32824461, 2020).
glaucoma (1 paper, 2023). Increased pressure in the eyeball due to obstruction of the outflow of aqueous humor. "Wnt signaling also activates Rac1, Racgap1, Iqgap3, and Dock2 genes in this pathway that were upregulated in three day glaucoma." (PMID 37762022, 2023).
immunodeficiencies (1 paper, 2024). "Their use may lead to chronic NFkB inhibition, which could result in immunodeficiencies and, in this case, NFkB activation due to IQGAP3 inhibition may be favorable for the overall homeostasis of skin." (PMID 38674130, 2024).
Pca (1 paper, 2022). "Some researches had found that the expression level of IQGAP3 in PCa was increased and the expression level of IQGAP3 correlated inversely with survivability, but the specific role of IQGAP3 in the occurrence and development of PCa is unclear." (PMID 36168930, 2022).
prostate adenocarcinoma (1 paper, 2023). "Analyses of TCGA-PRAD (prostate adenocarcinoma) data revealed 733 overexpressed genes, including IQGAP3, which is also frequently mutated." (PMID 36831467, 2023).